NAMPT (nicotinamide phosphoribosyltransferase)
Diseases named in the same sentence as NAMPT in open-access papers (continued):
Sharing a sentence is not in itself a finding about the gene and the disease.
neurodegenerative disease (6 papers, 2020 to 2025). A disorder of the central nervous system characterized by gradual and progressive loss of neural tissue and neurologic function. "Modulating NAMPT activity may offer a novel therapeutic strategy for treating neurodegenerative diseases associated with cholesterol dysregulation." (PMID 41041049, 2025). "Among them, oxidative stress is considered to be an important pathogenic factor in inducing cell proliferation, mitochondrial dysfunction, self-renewal and hypodifferentiation, and downregulation of NAD and NAMPT levels in neurodegenerative diseases." (PMID 39513038, 2024). "In the present review, we first introduced the structure and biological functions of NAMPT, as well as the close correlation between NAMPT and neurodegenerative diseases (e.g., AD and PD)." (PMID 35903330, 2022). "At present, the research on small molecule compounds to activate NAMPT is initiated in the infant stage, which requires in-depth explorations in the future, thus benefiting people who suffer from neurodegenerative diseases." (PMID 35903330, 2022). "The onset of ALS/PDC is associated with aging, similar to many neurodegenerative diseases, and the relationship between aging and nicotinamide (vitamin B3, NAD) biology, including NAMPT, is notable." (PMID 32422904, 2020). "Therefore, we believed that NAMPT is a very promising therapeutic target for neurodegenerative diseases." (PMID 35903330, 2022). "Strong neuroprotective efficacy in mouse models of chemotherapy-induced peripheral neuropathy without any apparent toxicity demonstrated the potential of NAMPT activator in treating neurodegenerative diseases or diseases associated with decreased NAD levels." (PMID 35903330, 2022). "Owing to the active biological function of NAMPT in neurogenesis, targeting NAMPT may be a powerful therapeutic strategy for neurodegenerative diseases." (PMID 35903330, 2022). "It is believed that NAMPT can be a promising therapeutic strategy for neurodegenerative diseases." (PMID 35903330, 2022). "However, effective NAMPT agonists or inhibitors in the application of neurodegenerative diseases are very scant." (PMID 35903330, 2022). "Therefore, NAMPT inhibitors are novel candidates for the treatment of neurodegenerative diseases." (PMID 35903330, 2022). "Furthermore, current agonists and inhibitors targeting NAMPT that are used for the treatment of neurodegenerative diseases were summarized for their molecule sources, characteristics, and therapeutic effects; thus, providing novel ideas for the targeted therapy of neurodegenerative diseases." (PMID 35903330, 2022). "The NAMPT-NAD-SIRT cascade has been identified as a powerful intrinsic defense system against energy expenditure and neuronal death in neurodegenerative diseases." (PMID 39513038, 2024). "Since NAMPT is the rate-limiting enzyme of the NAD salvage pathway in mammals, it can regulate neurodegenerative diseases by maintaining NAD homeostasis, cell metabolism, and mitochondrial function." (PMID 35903330, 2022). "The NAMPT–NAD–SIRT cascade, which is validated as a strong intrinsic defense system, fights against energy consumption and neuron death in neurodegenerative disease cases." (PMID 35903330, 2022). "Wang and colleagues showed that NAMPT plays an essential role in mitochondrial bioenergetics, motor function and survival and identified the NAMPT-mediated NAD+ salvage pathway as a potential therapeutic target for degenerative diseases." (PMID 33036437, 2020). "Compound 35 was shown to be an inhibitor of NAMPT (IC50 = 242.7 nM) by virtual screening based on structure and ligand, and showed a protective effect when tested in axonal cell models, suggesting that inhibition of NAMPT may be an effective treatment for neurodegenerative diseases." (PMID 35903330, 2022).
hematologic malignancies (4 papers, 2020 to 2023). "NAMPT inhibitors induce cell death in various cell lines of hematological malignancies." (PMID 36838885, 2023). "In this study, we report the synthesis and evaluation of the therapeutic efficacies of three novel NAMPT inhibitors, JJ08, FEI191 and FEI199, in hematological malignancies." (PMID 36838885, 2023). "Collectively, our findings demonstrate the efficient anticancer activity of the new NAMPT inhibitor JJ08 and highlight a strong interest for further evaluation of this compound in hematological malignancies." (PMID 36838885, 2023).
peripheral neuropathy (4 papers, 2017 to 2024). A disorder affecting the peripheral nervous system. "In line with the notion that skewed NMN/NAD+ can cause peripheral neuropathy, NAMPT inhibition using the novel agent A4276 was found to protect against Wallerian degeneration (during which NMNAT2 is downregulated) and peripheral neuropathy induced by vincristine and paclitaxel." (PMID 38396769, 2024). "The effectiveness of P7C3-A20 in our aggressive model of PTX-induced peripheral neuropathy highlights NAMPT-mediated NAD salvage as a new therapeutic target for CIPN." (PMID 29125463, 2017). "Interestingly, paclitaxel-induced peripheral neuropathy has also been reversed using NAMPT activators." (PMID 38396769, 2024). "However, FK886 completely blocked the protective effects of P7C3-A20 on PTX-induced mechanical allodynia and IENF degeneration, suggesting that NAMPT activity is required for the neuroprotective effect of P7C3-A20 on PTX-induced peripheral neuropathy." (PMID 29125463, 2017). "This suggests that P7C3-A20 may not prevent damage to peripheral sensory neurons by PTX but instead, by augmenting NAMPT activity, may maintain metabolic output of damaged neurons to allow time for repair mechanisms to reverse PTX-induced toxic damage and reduce the peripheral neuropathy." (PMID 29125463, 2017).
immune disorders (2 papers, 2017 to 2022). "NAMPT inhibition with FK866 has anti-inflammatory activity in different models of immune disorders through lowering the production of neutrophil chemoattractants." (PMID 28837586, 2017). "Visfatin/nicotinamide phosphoribosyltransferase (NAMPT) is an adipokine and an enzyme that is related to metabolic and immune disorders." (PMID 35701840, 2022).
myopathies (2 papers, 2020 to 2025). "Under exercise, or ageing and various myopathies, NAMPT levels correlate with NAD+/NADH ratio positively." (PMID 39901373, 2025). "Also, muscle-specific NAMPT KO mice are viable and only develop myopathy after several months despite NAD+ levels at 90-95% those of WT mice." (PMID 32075690, 2020).
blood cancers (1 paper, 2023). "We and others have demonstrated that NAMPT inhibitors exhibit high efficacy against a wide range of human solid tumors and blood cancers, without significant toxicity to laboratory animal models." (PMID 36838885, 2023).
brain diseases (1 paper, 2012). "Taken together, we have revealed a region- and cell-specific change of NAMPT level in brain and serum upon aging, deduced its potential consequences, which suggests that NAMPT is a regulatory factor in aging and age-related brain diseases." (PMID 23071504, 2012). "Hence, our findings suggest that NAMPT could be a regulatory factor in aging and age-related brain diseases." (PMID 23071504, 2012).
colonic polyps (1 paper, 2023). "The implications of extracellular nicotinamide phosphoribosyltransferase (eNAMPT) in colonic polyps remain uncertain." (PMID 36980589, 2023). "In situ probing of the NAMPT-associated pathway holds promise in attenuating PMP, as much of the eNAMPT likely originates from colonic polyps." (PMID 36980589, 2023).
infectious disease (1 paper, 2021). A disorder directly resulting from the presence and activity of a microbial, viral, or parasitic agent in humans. "Our study found that NAMPT levels were elevated in infectious pleural effusions, which was consistent with the reports of NAMPT in infectious disease." (PMID 34702907, 2021). "Nicotinamide phosphoribosyltransferase (NAMPT) has been reported to be involved in infectious diseases, but it is unknown whether it plays a role in infectious pleural effusions (IPEs)." (PMID 34702907, 2021).
NAMPT also shares sentences with these, for which no sentence is quoted: multiple myeloma (4 papers); systemic lupus erythematosus (4); B-cell chronic lymphocytic leukemia (3); anemia (2); atrial fibrillation (2); B-cell lymphomas (2); brain infarction (2); cancer of the stomach (2); cervical cancer (2); Coagulation Disorders (2); diffuse large B-cell lymphoma (2); follicular lymphoma (2); multiple sclerosis (2); neurological disease (2); Abdominal obesity (1); acute monocytic leukemia (1); adrenocortical carcinomas (1); age (1); Anxiety (1); autoimmune disorders (1); autoimmune encephalitis (1); breast invasive ductal carcinoma (1); bronchopulmonary dysplasia (1); carotid atherosclerosis (1); cerebral infarction (1); chronic lung disease (1); dementia (1); empyema (1); enterocolitis (1); esophagitis (1).
A further 59 diseases each share a sentence with NAMPT in 1 paper.